RHBDL2 (rhomboid like 2)
Description:
Regulator of proteosome activity independent of enzymatic activity. Involved in regulated intramembrane proteolysis and the subsequent release of functional polypeptides from their membrane anchors. Known substrate: EFNB3.
Synonyms: RRP2; FLJ20435
Tractability: Antibody: UniProt places it where antibodies can reach, with high confidence; its Gene Ontology location is reachable by antibodies, with high confidence; UniProt predicts a signal peptide or a membrane-spanning region. PROTAC: ubiquitination databases record sites on it.
Gene: Protein-coding gene on chromosome 1 (38,885,807 to 38,941,830, reverse strand). Ensembl gene ENSG00000158315.
Subcellular location: Cell membrane (Rhomboid-related protein 2, C-terminal fragment)
Gene Ontology:
Molecular function: serine-type endopeptidase activity
Cellular component: plasma membrane; membrane
Genetic constraint (gnomAD): Loss-of-function variants: 17 observed, 21.25 expected, observed/expected ratio (o/e) 0.8, 90% interval 0.55 to 1.2. The upper end of that interval is the gene's LOEUF score, 1.2, which puts it in group 5 of 6, group 1 being the genes least tolerant of losing a copy. Missense variants: 277 observed, 304.91 expected, observed/expected ratio (o/e) 0.91, 90% interval 0.82 to 1. Synonymous variants: 100 observed, 109.78 expected, observed/expected ratio (o/e) 0.91, 90% interval 0.77 to 1.08.
Homologues: Orthologues: chimpanzee RHBDL2 (100% identical), macaque RHBDL2 (98% identical), dog RHBDL2 (90% identical), pig RHBDL2 (90% identical), rabbit RHBDL2 (89% identical), guinea pig RHBDL2 (86% identical), mouse Rhbdl2 (85% identical), rat Rhbdl2 (85% identical), tropical clawed frog rhbdl2 (67% identical), zebrafish rhbdl2 (63% identical), Drosophila melanogaster rho-5 (25% identical), Caenorhabditis elegans rom-4 (21% identical), and 1 more. Paralogues in human: RHBDL1 (36% identical), RHBDL3 (35% identical), RHBDF1 (24% identical), RHBDF2 (24% identical), PARL (17% identical).
Diseases named in the same sentence as RHBDL2 in open-access papers:
RHBDL2 is named in the same sentence as 13 diseases in open-access papers, as found by Europe PMC text mining. Sharing a sentence is not in itself a finding about the gene and the disease. The quoted sentences say what the papers report.
breast carcinoma (6 papers, 2014 to 2025). "Furthermore, up-regulated RHBDL2 expression is associated with worse prognosis of several types of malignant tumors, such as breast cancer, pancreatic adenocarcinoma, clear cell kidney cancer, and low-grade glioma patient." (PMID 34318746, 2021). "RHBDL2 mRNA expression is markedly elevated in low-grade breast cancer tissues compared with that in normal breast samples." (PMID 36351890, 2022). "Indeed, patient sample analyses identified RHBDL2 as a prognostic marker in pancreatic cancer (PC), breast cancer, osteosarcoma, pancreatic ductal adenocarcinoma (PDAC), and colorectal cancer." (PMID 41015904, 2025). "It is necessary to further investigate whether RHBDL2 can be a therapeutic target in inhibiting the development and progression of breast cancer." (PMID 34318746, 2021). "Given that CSCs are crucial for breast cancer progression and metastasis, RHBDL2 may be a new therapeutic target for control of CD44-/CD24- cell conversion into CSCs to reduce CSC pool size and limit breast cancer progression and metastasis." (PMID 34318746, 2021). "The RHBDL2 protein levels of the highly invasive breast cancer cells (MDA-MB-231 cells) or cervical cancer cells adapted to grow in suspension cultures (HeLa S3 cells), as revealed by the Western blotting analysis, were increased in a time-dependent manner during 48-hour suspension cultures." (PMID 24977233, 2014). "In contrast, RHBDL2 has been shown to delay cancer progression, with its upregulation being required for the spontaneous conversion of CD44−/CD24− breast cancer cells into CD44+/CD24− cancer stem cells in patient‐derived samples." (PMID 41015904, 2025). "Human rhomboid-like 2 (RHBDL2) is differentially expressed in cervical and breast cancer." (PMID 36351890, 2022). "The most important of the rhomboids are RHBDL2 (Rhomboid-related protein 2), which can trigger the activation of the EGF receptor and has been found to be highly expressed in breast cancer and RHBDL4 (Rhomboid-related protein 4), which triggers non-canonical secretion of TGFα." (PMID 33802262, 2021).
osteosarcoma (5 papers, 2023 to 2026). A usually aggressive malignant bone-forming mesenchymal neoplasm, predominantly affecting adolescents and young adults. "The KM curve indicated that DOK2 acted as a protective factor, whereas NPW and RHBDL2 functioned as risk factors, all of which were associated with the survival rate of osteosarcoma patients." (PMID 40668798, 2025). "Analysis of patient samples in The Cancer Genome Atlas (TCGA) revealed that RHBDL2 contributes to high infiltration of cancer‐associated fibroblasts in osteosarcoma." (PMID 41015904, 2025). "We demonstrated the results by IHC experiments, and observed that CGREF1, CORT and RHBDL2 proteins expression were high in the tissue of osteosarcoma patients, while the proteins were lowly expressed in normal tissue." (PMID 37441535, 2023). "Under a confocal microscope, RHBDL2 was found to be mainly distributed in the membrane and cytoplasm, with higher expression in Osteosarcoma cells than in normal cells." (PMID 38180104, 2023). "In addition, it was also observed that the protein of RHBDL2 was significantly increased in Osteosarcoma cell lines compared with normal cells." (PMID 38180104, 2023).
pancreatic cancer (2 papers, 2022 to 2025). "Furthermore, RHBDL2 plays a crucial role in pancreatic cancer, where it enhances proliferation, migration, and invasion by stabilizing N1ICD through interactions with OTUD7B and activation of the Notch signalling pathway." (PMID 40668798, 2025).
osteoarthritis (1 paper, 2025). A noninflammatory degenerative joint disease occurring chiefly in older persons, characterized by degeneration of the articular cartilage, hypertrophy of bone at the margins and changes in the synovial membrane. "For instance, shedding of TM by RHBDL2 in chondrocytes decreases inflammation and osteoarthritis in mice, and suppression of RHBDL2‐mediated cleavage of TM induced by high glucose conditions prevents efficient bone healing in diabetic mice." (PMID 41015904, 2025). "Nevertheless, results from systemic expression analyses are offering new insights on RHBDL2's systemic functions where it is postulated to be involved in osteoarthritis, reproductive success, and natural menopause." (PMID 41015904, 2025). "A vertebrate knockout model would provide a foundation for understanding how dysregulation of RHBDL2 drives pathologies such as cancer, regenerative defects, inflammation, and osteoarthritis." (PMID 41015904, 2025).
prostate carcinoma (1 paper, 2019). A carcinoma that arises from epithelial cells of the prostate gland. "In a high throughput functional screening in PC3 prostate carcinoma cells, the knock-down of intramembrane protease gene RHBDL2 was serendipitously found to inhibit cell migration." (PMID 31783481, 2019). "By a complementary approach, we overexpressed RHBDL2 in PC3 cells, as well as in another prostate carcinoma model, DU145, characterized by low endogenous levels of the protease." (PMID 31783481, 2019). "RHBDL2 is well expressed in diverse cancer cell lines; however, we found that its levels are basally low in DU145 prostate cancer cells and endothelial cells." (PMID 31783481, 2019).
Stormorken syndrome (1 paper, 2021). Stormorken-Sjaastad-Langslet syndrome is characterized by thrombocytopathy, asplenia, miosis, muscle fatigue, migraine, dyslexia, and ichthyosis. "Significantly, the major determinant of RHBDL2 recognition of Orai1, proline-245, is the causative mutation of the rare inherited Stormorken syndrome, which is characterized by excess CRAC channel activity." (PMID 34800360, 2021). "Furthermore, our work reveals that RHBDL2 has strongly diminished ability to recognize and cleave a Stormorken syndrome-causing mutant Orai1 (P245L)." (PMID 34800360, 2021).
triple-negative breast carcinoma (1 paper, 2019). An invasive breast carcinoma which is negative for expression of estrogen receptor (ER), progesterone receptor (PR), and human epidermal growth factor receptor 2 (HER2). "Thus, we decided to focus on RHBDL2 by performing new independent gene silencing experiments in the PC3 cells, and confirming its functional relevance in another invasive cancer cell line, the triple-negative breast carcinoma cells MDA-MB468 characterized by a high expression of the protease." (PMID 31783481, 2019).
tumor (8 papers, 2014 to 2026). "Notably, RHBDL2 also functions as a critical component of cancer-associated fibroblasts, a prominent element within the tumor microenvironment with versatile roles in tumor progression." (PMID 40668798, 2025). "Together, these findings uncover Rhbdl2 as an immune checkpoint that constrains macrophage-driven enhanced regeneration, with vast implications for inflammatory disease, fibrosis, and tumor-immune interactions." (PMID 41726946, 2026). "In various tumor cell lines, endogenous RHBDL2 activity has been observed, where it cleaves EGF just outside its transmembrane domain, promoting its secretion and triggering EGFR activation." (PMID 40668798, 2025). "Concordantly, the expression level of RHBDL2 was examined by conducting qRT-PCR and western blot assays of PC tissues and adjacent non-tumor tissues, which showed that the RHBDL2 was upregulated in PC tissues." (PMID 36351890, 2022). "The RHBDL2 overexpression group showed higher tumor weight and volume, while the RHBDL2 knockdown groups had lower tumor weight and volume." (PMID 36351890, 2022). "The upregulation of RHBDL2 expression facilitated tumor growth, while RHBDL2 silencing led to the inhibition of tumor growth." (PMID 36351890, 2022). "There were 11 DEGs associated with tumor cell differentiation and dedifferentiation between EGFP- CD44-/CD24- cells and EGFP+ CSCs and they included RHBDL2, HIST1H4H, DSCC1, ZNF710, ATP8B3, and others." (PMID 34318746, 2021). "Another cell surface protein that is found to be cleaved by RHBDL2 in (non-tumor) epithelial cells is thrombomodulin." (PMID 31783481, 2019). "Therefore, it is reasonable that overexpression of RHBDL2 may be associated with reduction of cell adhesion and subsequent tumor spreading, but the precise mechanism for detached tumor cells to reachieve cell adhesion during metastasis to a new environment needs further studies." (PMID 24977233, 2014). "It has been reported that endogenous RHBDL2 in tumor cell lines can activate the EGFR through the release of EGF." (PMID 24977233, 2014). "During long-term suspension cultures, increased RHBDL2 was only detected in aggressive tumor cell lines." (PMID 24977233, 2014). "By analyzing the published mRNA expression profiles (GSE16515, GSE28735, and GSE15471) acquired from the Gene Expression Omnibus database, we discovered that the RHBDL2 mRNA was noticeably upregulated in PC tissues compared with that in normal/non-tumor tissues." (PMID 36351890, 2022). "Moreover, IHC staining showed high RHBDL2, Ki-67, and PCNA expression levels in tumor tissues with RHBDL2 upregulation." (PMID 36351890, 2022). "Interestingly, we discovered that RHBDL2 expression is specifically induced in tumor cells by the inflammatory signal TNFα, which leads to E-cadherin cleavage and shedding." (PMID 31783481, 2019). "Subsequently, we investigate whether RHBDL2 is increased in malignant tumor cells in prolonged suspension cultures." (PMID 24977233, 2014). "Our study showed the association between RHBDL2-mediated anoikis resistance and the activation of EGFR and FAK, and these findings may provide possible mechanisms by which detached tumor cells activate EGFR and acquire anoikis resistance." (PMID 24977233, 2014). "Compared with the unconverted CD44-/CD24- tumor cells, PPME1, RHBDL2 and HIST1H4H mRNA transcripts increased in the newly converted CD44+/CD24- CSCs with a change of >two folds, which were similar to that in parental CD44+/CD24- CSCs." (PMID 34318746, 2021). "Our study suggests that RHBDL2 is a key modulator in EGFR activation and anoikis resistance in homeless tumor cells." (PMID 24977233, 2014). "AS events of TMC7 and RHBDL2 showed higher expression in the primary PDAC tumor without liver metastasis." (PMID 36713450, 2022). "In this study, we report for the first time that the extracellular domain of E-cadherin is shed by RHBDL2 protease expressed in tumor (and non-tumor) cells." (PMID 31783481, 2019).
tumor (continued). "Upregulation of RHBDL2 was only detected in highly malignant or transformed tumor cells but not in tumor cells with low invasive or adaptive potentials." (PMID 24977233, 2014).
cancer (6 papers, 2014 to 2025). A tumor composed of atypical neoplastic, often pleomorphic cells that invade other tissues. "Indeed, the loss of function approaches in our experiments indicated that MMPs and RHBDL2 protease are both implicated for E-cadherin targeting in cancer cells." (PMID 31783481, 2019). "RHBDL2, a member of the rhomboid protein family, plays a multifaceted role in keratinocyte proliferation, and its involvement in cancer has been documented." (PMID 40668798, 2025). "Beyond its role in cancer, RHBDL2 is also being explored in the context of other diseases, especially those affecting bone tissue." (PMID 41015904, 2025). "Here, we show a novel mechanism of post-translational regulation of E-cadherin in cancer cells by an intramembrane protease of the Rhomboid family, RHBDL2, which leads to the shedding of E-cadherin extracellular domain." (PMID 31783481, 2019). "Of note, also in this case, the cell morphology or growth rates were not affected, which validates our conclusion that RHBDL2 controls a mechanism that specifically regulates cancer cell migration." (PMID 31783481, 2019). "Our findings open the stimulating prospect that the development of selective RHBDL2 inhibitors will enable their application in cancer therapy regimens, with the aim of hindering cancer cell migration." (PMID 31783481, 2019). "In fact, upon RHBDL2-dependent cleavage of E-cadherin on the cell surface, cancer cell migration increased, likewise in response to E-cadherin knock-down, and independent of the regulation of cell-cell adhesion." (PMID 31783481, 2019). "In keeping with Western blotting data, RHBDL2 protease greatly reduced cell surface E-cadherin in both cancer cell models, although this was expectedly more evident in DU145." (PMID 31783481, 2019). "In particular, we observed that the E-cadherin protein levels markedly decreased in PC3 cancer cells upon RHBDL2 overexpression, while they conversely increased upon silencing the protease; notably, these changes were independent of transcriptional regulation." (PMID 31783481, 2019). "Here, we report the finding of a novel relevant substrate of RHBDL2 protease in cancer cells, E-cadherin." (PMID 31783481, 2019). "We observe substantial variation in the gene expression of RHBDL2 and the substrates we identify here in several cancer studies, particularly in RHBDL2-rich tissues such as the skin, airways and digestive tract." (PMID 28779096, 2017). "RHBDL2 plays a major role in cancer progression and is a potential marker for various carcinomas." (PMID 41015904, 2025). "While mechanistic links to these different cancers are yet to be elucidated, it is likely that RHBDL2‐mediated cleavage of certain substrates such as CLCP1 may contribute to cancer progression." (PMID 41015904, 2025). "There are marked differences in RHBDL2's mechanism of action in different cancers." (PMID 41015904, 2025). "Indeed, we found a remarkable induction of RHBDL2 expression by TNFα in both endothelial and cancer cells." (PMID 31783481, 2019). "Interestingly, we found that TNFα induced E-cadherin cleavage and extracellular shedding in DU145 cancer cells, which was dependent on the upregulation of endogenous RHBDL2, as demonstrated by the gene knock-down experiments." (PMID 31783481, 2019). "In addition, our data suggest that RHBDL2 activity controls cancer cell migration by E-cadherin functional inactivation." (PMID 31783481, 2019). "Thus, we aimed at stripping MMP-activity in DU145 cancer cells by means of the broad inhibitor Marimastat, which is ineffective on intramembrane protease RHBDL2." (PMID 31783481, 2019). "However, very little was known about the actual functional impact of RHBDL2 protease in cancer cells." (PMID 31783481, 2019). "Thus, our findings implicate RHBDL2 as a novel negative regulator of E-cadherin function in cancer cells." (PMID 31783481, 2019). "Our study demonstrates RHBDL2 as a new therapeutic target for cancer metastasis." (PMID 24977233, 2014).
cancer (continued). "It is currently unknown how the RHBDL2 levels are regulated in cancer context." (PMID 31783481, 2019). "While RHBDL2 appeared as the main effector of TNFα-induced E-cadherin cleavage, our data showed that a basal level of E-cadherin shedding was visible and maintained in cancer cells also upon RHBDL2 depletion, being presumably accountable by the activity of diverse MMPs." (PMID 31783481, 2019). "Thus, we considered the possibility that RHBDL2 might have additional unexpected substrates in cancer cells." (PMID 31783481, 2019). "Moreover, TNFα treatment induced PC3 cell migration, but such an effect was blunted upon RHBDL2 silencing, which suggested that this protease might act as downstream effector of the cytokine in the regulation of cancer cell migration." (PMID 31783481, 2019). "RHBDL2 in DU145 carcinoma cells indued similar effects, which express higher basal levels of E-cadherin; thus, we could also detect a striking increase in the shedding of soluble E-cadherin extracellular domain in the conditioned medium of these cells, in response to RHBDL2 expression." (PMID 31783481, 2019). "Yet, although RHBDL2-dependent EGF activation was proposed to impact cancer cell functions, this mechanism was not further investigated." (PMID 31783481, 2019). "Intriguingly, while the migration of certain cancer cells that were reliant on RHBDL2 was essentially independent of MMP activity, for others the migration was conditioned by MMPs, both basally and upon RHBDL2 upregulation." (PMID 31783481, 2019). "Intriguingly, we extensively tested, in vain, the ability of the conditioned medium of RHBDL2 overexpressing cells to trigger cancer cell migration (and data not shown)." (PMID 31783481, 2019). "Notably, cancer therapeutic approaches that are based on MMP-specific inhibitors have failed to achieve significant success, possibly due to redundant functions that are mediated by RHBDL2 protease induced upon tissue inflammation." (PMID 31783481, 2019). "Moreover, while considering its reported activity in EGF shedding, we specifically analyzed EGFR activation in cells overexpressing RHBDL2, but could not confirm this mechanism in our cancer cell models." (PMID 31783481, 2019).
infection (1 paper, 2025). The state of being infected such as from the introduction of a foreign agent such as serum, vaccine, antigenic substance or organism. "Compared with that observed post-infection with wild-type (WT) HBDL2 FCV, a minimal level of VP1 expression was observed at 12 h post-infection with rHBDL2 FCV-△VP2." (PMID 40626663, 2025).
RHBDL2 also shares sentences with these, for which no sentence is quoted: glioma (2 papers); pancreatic adenocarcinoma (2); cervical cancer (1).